ESR1 (estrogen receptor 1)
Diseases named in the same sentence as ESR1 in open-access papers (continued):
Sharing a sentence is not in itself a finding about the gene and the disease.
breast cancer (continued). "It was difficult to confirm in this study whether there was a difference in sensitivity to ET due to the high E380Q mutation rate or the presence of ESR1 mutations in patients with de novo stage IV breast cancer." (PMID 33692409, 2021). "This prediction was validated in CCLE group of breast cancer cell lines, where both the expression levels of PD-L1 and corresponding ssGSEA scores of PD-L1 associated gene set were significantly negatively correlated to ESR1 expression levels." (PMID 34975907, 2021). "Additionally, the open-label, phase 2a, plasmaMATCH trial showed that FUL alone was ineffective in patients with advanced breast cancer and ESR1 mutations, in agreement with our finding of low activities of FUL in ESR1-mutated models." (PMID 33980285, 2021). "Interestingly, the receptor tyrosine kinase RON, which is expressed on resident macrophages, has been recently shown to promote endocrine therapy resistance in ESR1 mutated breast cancers." (PMID 34717714, 2021). "The expression of estrogen receptor (ESR1, encoded by ESR1 gene) defines luminal breast cancers." (PMID 34685621, 2021). "The ESR1 mutation status of breast cancer is associated with resistance to endocrine therapy." (PMID 33968723, 2021). "In addition, breast cancers with ESR1 mutations can gain a basal-like gene expression profile and enhanced M2-like macrophage immune activation that is associated with poor prognosis." (PMID 34717714, 2021). "ESR1 mutations have been found in 10–40% of advanced breast cancers." (PMID 33670042, 2021). "An analysis of tumors with the most recurrent outlier loss, ESR1, revealed concurrent upregulation of genes typically expressed in basal breast cancers, such as PROM1, KLK7, and NDRG1, suggesting a selection of a more basal-like phenotype in endocrine-resistant disease." (PMID 33407744, 2021). "This study identifies a gene signature diagnostic for functional ESR1 fusions that drive poor outcome in advanced breast cancer, which could also help guide precision medicine approaches in patients harboring ESR1 mutations." (PMID 34711608, 2021). "Interestingly, few of the ESR1 mutations observed in breast cancer metastatic samples correspond to phosphorylatable residues (Y537, for example) suggesting relevance of these phosphorylations in ERα function." (PMID 33498407, 2021). "The age at menarche before 14 years old was associated with the high risk of breast cancer, and the risk was higher when subjects had homozygous minor allele G. The second GxE was shown between rs851998 near ESR1 and height in the GE|2df model (p-2df = 1.1 × 10−4)." (PMID 34069208, 2021). "Thus, ESR1 mutations in HR-positive breast cancer occur almost exclusively after AI in the metastatic setting." (PMID 34392831, 2021). "Consistent with our genomic comparison between primary and metastasis, the ESR1 mutation is found by the mean SHAP value as the most predictive feature of metastatic breast cancer, followed by FGFR4 mutation, SOX2 amplification, ERBB2 mutation, and FGFR1 mutation." (PMID 34795255, 2021). "It has been suggested that ESR1 mutations may usually be subclonal in the resistant breast cancer cells arising in response to ET, yet the effect of this subclonality in response to therapy is unknown." (PMID 34771560, 2021). "With the inhibition of ESR1, the risk of hormone breast cancer would be diminished." (PMID 34055017, 2021).
breast cancer (continued). "Key examples include EGFR-T790M mutations and resistance to EGFR inhibitors in EGFR-mutant lung cancer, ESR1 mutations in estrogen receptor positive breast cancer treated with endocrine therapy, and reversions of pathogenic mutations in BRCA1 and BRCA2 deficient cancers treated with PARP inhibitors." (PMID 34680271, 2021). "Importantly, several studies have shown that the ESR1 mutations can be selected during AI treatment of metastatic HR+ breast cancers, which can be detected in ctDNA." (PMID 33322643, 2020). "To showcase our method, we evaluate associations between breast cancer susceptibility and SNPs in estrogen receptor alpha (ESR1), fibroblast growth factor receptor 2 (FGFR2), RAD51 homolog B (RAD51B), and TOX high mobility group box family member 3 (TOX3) genes, without access to raw genotype data." (PMID 32287273, 2020). "ESR1 may serve to develop a hormonal therapy for breast cancer, since ESR1 gene mutating is related to acquired endocrine resistance in patients with ER-positive metastatic breast cancer." (PMID 32368784, 2020). "Additionally, BPA lowers Esr1 (ERα) and augments Esr2 (ERβ), whose expression is linked to increased risk of breast cancer." (PMID 33330580, 2020). "In addition, breast cancer cells unresponsive to endocrine therapy exhibit acquired activating mutations on ESR1 gene driving an increased unliganded activation of ERs presumably as a key for their survival." (PMID 32774370, 2020). "ESR2, like ESR1, contains multiple polymorphisms that have been implicated in diseases related to old age and reproduction, as related to bone mineral density, cancers of the breast and ovary and hypertension and cardiovascular risk." (PMID 32593802, 2020). "In addition, the immunogenicity of epitope derived from the most common ESR1 mutations including D538G and Y537S was suggested as novel targets for breast cancer immunotherapy." (PMID 33233830, 2020). "However, the underlying molecular mechanism of ESR1 in ERα positive breast cancer remains insufficiency." (PMID 32500028, 2020). "Based on our included studies, ddPCR technologies are increasingly being used for the detection of ESR1 mutations in advanced breast cancers owing to the enhanced sensitivity of ddPCR, which enables more accurate positive detection of ESR1 mutations in plasma samples." (PMID 33233830, 2020). "In the same vein, we observed a lower prevalence of ERBB2 amplification in this breast cancer patient cohort compared to that in a general population (3 vs. 10–15%, respectively) but a higher incidence of ESR1 mutations associated with progression on hormone-based therapies." (PMID 31019892, 2019). "Some ESR1 genetic differences were described between different dog breeds known to be at high and at low risk of mammary tumor development; furthermore, an association between ESR1 variation and the susceptibility to mammary tumors was described in a cohort of English Springer Spaniels." (PMID 31506083, 2019). "There are many mutations of the ESR1 gene reported in treatment refractory breast cancers." (PMID 31749762, 2019). "Out of 77 breast cancer samples, 11 (14.3%) showed mutations in the ESR1 gene." (PMID 31511774, 2019). "ER, a protein encoded by the ESR1 gene, is expressed in the majority of breast cancers." (PMID 31511774, 2019). "However, mutations in ESR1 enhancer sequences found in ~ 7% of breast cancers have now been shown to be responsible for altering ESR1 expression by modulating TF binding activity." (PMID 31304632, 2019). "Moreover, the amplification of ESR1 was shown to be linked with good prognosis in tamoxifen-treated breast cancer patients." (PMID 30995757, 2019). "CDK4/6 inhibitors have also been tested in PDX breast cancer models harboring ESR1 point mutations." (PMID 31106278, 2019). "However, very few functionally significant ESR1 fusions have been studied to date and therefore ESR1 fusion events remains an understudied form of somatic mutation in breast cancer." (PMID 31106278, 2019).
breast cancer (continued). "Interestingly, studies have shown that ESR1 amplification in a subset of ER+ breast cancers were associated with tamoxifen resistance and poor prognosis." (PMID 31106278, 2019). "Different ESR1 mutations in a single CTC were also tested in breast cancer." (PMID 31650022, 2019). "Furthermore, the presence of ESR1 point mutations predominately appear in late-stage breast cancer patients that have been treated with multiple lines of endocrine therapies but rarely in treatment naïve cases." (PMID 31106278, 2019). "Finally, gene network analysis revealed that p52SHC KO disrupted multiple key pathways that have been previously implicated in breast cancer initiation and progression, including ESR1 and mTORC2/RICTOR." (PMID 31202267, 2019). "ESR1 encodes oestrogen receptor α, which is a significant part of the nuclear hormone receptor family and is expressed in over two-thirds of patients with breast cancer." (PMID 31391089, 2019). "ESR1 mutated recurrent breast cancer has become a focus of attention in the possible development of new agents, such as selective oestrogen receptor degraders but very little has been reported on the phenotype of the ESR1-mutated tumours." (PMID 30563991, 2019). "Moreover, studies are ongoing to clarify the activity of novel drugs in the context of metastatic endocrine resistant luminal breast cancer harboring ESR1 mutations." (PMID 31795152, 2019). "GJA1 encodes for connexin-43, a gap junction protein whose expression in breast cancer cells has been implicated in pulmonary metastasis, consistent with observed lung metastasis in both patients from which the ESR1-e6>YAP1 and ESR1-e6>PCDH11X fusions were identified." (PMID 30089255, 2018). "ESR1 encodes an estrogen receptor with important and drug-gable relevance to breast cancer." (PMID 29617662, 2018). "It should, however, be noted that splice variants of ESR1 in breast cancer differ importantly from splice variants of the AR, as ESR1 splice variants are also expressed in healthy breast tissue, and full‐length AR and splice variants are typically absent in CellSearch‐enriched fractions of HBDs." (PMID 29063679, 2018). "While it has already been recognized that primary breast cancers rarely harbor ESR1 mutations, most studies thus far have evaluated patients who had been pretreated with palliative endocrine therapy, suggesting that these mutations become enriched during treatment with AIs." (PMID 29063679, 2018). "The opposing associations of AGR2 and ESR1 expression with DSS could reflect the role of AGR2 in hormone therapy- resistant ER+ breast cancer: ER+ breast cancers may develop resistance by overexpressing AGR2." (PMID 29796176, 2018). "The driver mutations directly connected to the activation of ESR1 expression remain unclear in luminal subtype breast cancers." (PMID 30375428, 2018). "However, ERα loss and ESR1 mutation have been detected in metastatic relapse of ERα-positive breast cancer." (PMID 30301189, 2018). "Thus, our PDX data support a potential new treatment regime for breast cancers bearing ESR1 LBD mutations, which is to combine a SRC inhibitor with an oral SERD." (PMID 29748621, 2018). "Here, we performed whole-exome sequencing of 16 breast cancer tissues classified according to ESR1 expression and 12 samples of whole blood, and detected 310 somatic mutations in cancer tissues with high levels of ESR1 expression." (PMID 30375428, 2018). "Our data indicate that abiraterone may have context-dependent roles in ER+ breast cancer that can be influenced by prior hormonal therapies and that ESR1 mutation status may influence its efficacy in the clinical setting." (PMID 29991699, 2018). "Y537S ESR1 mutation has been found in recurring advanced breast cancer at high frequency." (PMID 29467940, 2018). "The SNP mapped to the pathways through ESR1 may also be associated with variations in breast cancer between YRI and CEU populations." (PMID 28445522, 2017).
breast cancer (continued). "The discovery of recurrent ESR1 mutations within the region of the gene that encodes the ER-LBD in endocrine-resistant ER+ advanced breast cancer introduced new clinical challenges and opportunities for the understanding of the mechanisms of endocrine resistance." (PMID 28361033, 2017). "Moreover, a recent investigation has suggested that mutational activation of ESR1 plays an important role in acquired endocrine resistance during breast cancer therapy." (PMID 28472954, 2017). "The risk allele of six SNPs was the same for both breast cancer and endometriosis, including four SNPs (rs851981, rs851980, rs2206948 and rs150182883) that are in strong LD (r2≥0.60) with our secondary association signal rs2206949 at 6q25.1 (ESR1)." (PMID 28537267, 2017). "ESR1 can be suggested as a key gene to investigate the mechanisms of breast cancer cause by EDCs." (PMID 28973975, 2017). "In addition, recent investigations have suggested that mutations that activate ESR1 play an important role in acquired resistance to hormonal therapy and the preference towards bone metastasis among breast cancer patients (ASCO, annual meeting, 2016)." (PMID 28472954, 2017). "Characteristics of all of the eligible studies of the ESR1 polymorphisms and breast cancer." (PMID 27070141, 2016). "Numerous studies suggest an association between ESR1 gene polymorphisms and breast cancer risk." (PMID 27825388, 2016). "While somatic mutations in the androgen receptor are a known mechanism of acquired hormone therapy resistance in prostate cancer, somatic mutations in ESR1 have only recently been identified as an important mechanism of acquired endocrine therapy resistance in breast cancer." (PMID 26836308, 2016). "We hypothesize that ESR1 may play a role in the relationship between dense breast tissue and estradiol levels, and therefore, the risk of breast cancer." (PMID 27717337, 2016). "Specific polymorphisms (SNPs) in ESR1 may directly or indirectly lead to variations in its activity, and may have an effect on breast cancer risk." (PMID 27717337, 2016). "Consistently, DDX3X also statistically associates with ESR1 in breast cancer." (PMID 26184164, 2015). "Thus, ESR1 (estrogen receptor 1), which encodes for a hormone-activated transcription factor, was significantly down-regulated in the primary mouse mammary tumors." (PMID 26059540, 2015). "Within ER+ breast cancer higher expression of ESR1 is also associated with good prognosis." (PMID 26183823, 2015). "In addition, two identified genes, GABRP, positively associated with young breast cancer, and ESR1, down-regulated in young breast cancer, were also included." (PMID 25990390, 2015). "ESR1 encodes the estrogen receptor alpha and contributes to cell growth in breast carcinoma." (PMID 26099425, 2015). "In this report, estrogen receptor (ESR1) had defined the relation of hormone-cause breast cancer." (PMID 25054138, 2014). "In the present study, we genotyped six potentially functional single-nucleotide polymorphisms (SNPs) within the CCDC170 and ESR1 gene regions at 6q25.1 and accessed their associations with risk of breast cancer in a study of 1,064 cases and 1,073 cancer-free controls in Chinese women." (PMID 25116933, 2014). "Our findings of acquired ESR1 mutations in metastatic, endocrine therapy-resistant breast cancers have been independently corroborated by other groups and have been described previously by Li and colleagues in ER-positive xenografts derived from poor-prognosis, treatment-resistant tumors." (PMID 25928204, 2014).
breast cancer (continued). "In one of the first reports of acquired ESR1 mutations in human breast cancers, Fuqua and coworkers in 1997 described a nonsynonymous mutation in Tyr537 (Y537N) in a study of 30 metastatic breast cancer tumors and implicated this mutation in hormone-independent constitutive activation of the ER." (PMID 25928204, 2014). "Since the contiguous relations between rs2046210 and ESR1, researchers hypothesize that it was the polymorphism itself or the causal variants in LD that might regulate ESR1 gene expression and contribute to be elevated susceptibility to breast cancer." (PMID 25531440, 2014). "The higher rate of ESR1 mutations in primary tumors (3%) in this study is probably related to the fact that patients enrolled in the BOLERO-2 clinical trial had advanced breast cancer and had disease progression or recurrence after treatment with an aromatase inhibitor (letrozole or anastrozole)." (PMID 25928204, 2014). "Given the prior evidence that ESR1 plays a role in human breast cancer etiology, it seems probable that the described loci of the present study might be correlated with a causal variant affecting ESR1 function." (PMID 23574728, 2013). "ESR1 codes for the estrogen receptor α, and variations may be associated with risk of breast cancer." (PMID 24312387, 2013). "We found that ESR1 binding sites were strongly enriched near regions associated with susceptibility to breast cancer, height, MS and prostate cancer, suggesting that ESR1 may contribute to the functional genomics of these diseases." (PMID 24171864, 2013). "In conclusion, our data confirm the prognostic (or predictive) significance of ER mRNA and protein expression in high-risk early breast cancer and highlight the heterogeneous nature of ESR1 gene copy number aberrations with respect to regulatory and functional impact on the cancer cell." (PMID 23923010, 2013). "In the present study, we aimed to investigate whether ESR1_TA, ESR2_CA, and AR_CAG could be breast cancer susceptibility markers in African American (AA) and Nigerian (NG) women." (PMID 22792352, 2012). "Our study also suggests that genetic variants in the ESR1 gene and chromosome 11q24.3 may be related to breast cancer risk." (PMID 22383897, 2012). "A previous study has associated targeting of ESR1 by miR-302c with a role in breast cancer." (PMID 23049969, 2012). "Thus, the role of germline genetic variants of ESR1 in breast cancer etiology herein remains to be further clarified and explored." (PMID 22792352, 2012). "In particular the potential interaction between height and rs851987 in ESR1 in relation to breast cancer risk could merit further investigation." (PMID 22726230, 2012). "Genetic variants in hormone receptor genes may be crucial predisposing factors for breast cancer, and microsatellites in the estrogen receptor (ESR1, ESR2) and androgen receptor (AR) genes have been suggested to play a role." (PMID 22792352, 2012). "The well-known mechanism in which ER binds to EREs to mediate the expression of ER-regulated genes prompted us to speculate whether the SNPs of EREs and ESR1 might be jointly associated with breast cancer." (PMID 21281495, 2011). "Our investigation of factors associated with the level of expression of ESR1 in ER+ve tumours has revealed unexpected associations between genes in this region and ESR1 expression that are important to consider in studies of the genetic causes of breast cancer risk." (PMID 21552322, 2011). "Given that a large association study of ESR1 by the Breast Cancer Association Consortium also revealed a significant association within the same region under a dominant model, we searched for SNPs that were in high LD (r2 > 0.5) with the three haplotypes but were not genotyped in our previous study." (PMID 21269472, 2011). "Genetic variants immediately upstream of ESR1 have recently been linked to breast cancer risk." (PMID 21552322, 2011).